ACSL4 (acyl-CoA synthetase long chain family member 4)
Diseases named in the same sentence as ACSL4 in open-access papers (continued):
Sharing a sentence is not in itself a finding about the gene and the disease.
tumor (continued). "This study demonstrates that BQ323636.1 (BQ) drives lipid metabolism in ER-positive breast cancer by upregulating ACSL4 through disruption of the NCOR2-PPARγ interaction, enhancing FAO to fuel tumor growth." (PMID 40507798, 2025). "PPARγ, a key regulator of lipid metabolism, directly binds to the ACSL4 promoter, and its de-repression by BQ amplifies FAO, fueling tumor growth and proliferation." (PMID 40507798, 2025). "In breast cancer and glioblastoma, CAFs disrupt the ferroptosis pathway by secreting miR-454-3p (targeting lipid metabolism enzyme ACSL4) and upregulating lncRNA DLEU1, promoting tumor survival." (PMID 40755775, 2025). "Double repression of ACSL4 and enoyl-CoA hydratase 1 (ECH1) markedly reversed the metastasis of tumor cells." (PMID 41188993, 2025). "Arachidonic acid and IFN-γ facilitate the upregulation of ACSL4 expression by activating the STAT1 and IRF1 signaling pathways, ultimately leading to ferroptosis induction in tumor cells." (PMID 40140647, 2025). "By dampening the FOXO3a–ACSL4 axis, AIM2 reduces membrane PUFA-PL content and blunts lipid peroxidation, enabling tumor cells to evade ferroptosis." (PMID 41425591, 2025). "In liver cancer cells, high lactate levels can increase the level of MUFAs in the cell membrane and down-regulate the expression of ACSL4 through the AMPK pathway, thus effectively inhibiting ferroptosis in tumor cells." (PMID 40169575, 2025). "For example, compared with wild-type mice, ACSL4-knockout mice exhibited reduced CD8+ T cell infiltration in tumors, decreased IFN-γ and TNF-α expression, lower tumor cell lipid peroxide levels, and accelerated tumor growth." (PMID 41035634, 2025). "Collectively, these findings demonstrate that COP1 suppresses ferroptosis and drives tumor progression in RCC in vivo, with ACSL4 downregulation and enhanced proliferation serving as critical mechanisms." (PMID 40395328, 2025). "During tumor immunotherapy, IFN-γ released by activated CD8 + T cells also upregulates the expression of ACSL4 in tumor cells through the STAT1-IRF1 signaling pathway." (PMID 38965216, 2024). "To explore how macrophage M2 restores the sensitivity of tumor cells to radiotherapy-induced ferroptosis through EMT, we investigated the expression levels of the ferroptosis-related protein ACSL4, which is activated by the Hippo pathway during EMT." (PMID 38340316, 2024). "Immunohistochemical evaluation revealed a mild increase in pro-ferroptotic enzymes like acyl-CoA-synthetase 4 (ACSL4) and a significant, 3-fold decrease in glutathione peroxidase-4 (GPx4) in recurrent GBM tumors relative to the corresponding primary tumor." (PMID 39709480, 2024). "Consistently, depletion of ACSL4 and GPx4 overexpression has been shown to diminish GBM tumor necrosis and aggressiveness in pre-clinical models of GBM." (PMID 39709480, 2024). "In this study, big data analysis revealed that PCBP1, ACSL4, and ALOX15 were differentially expressed in both tumor and normal tissues of NSCLC." (PMID 39845670, 2024). "In the tumor microenvironment, arachidonic acid, in combination with IFNγ produced by CD8+ T cells, induces tumor ferroptosis in an ACSL4-dependent manner." (PMID 39402302, 2024). "We established a subcutaneous tumor model in mice using the DU145 and C4-2B cell lines with an ACSL4 knockdown." (PMID 39261475, 2024). "Significant positive correlations with GPX4 (ferroptosis), ACSL4 (fatty acid metabolism), SOD2 (antioxidant), HIF1A (tumor growth and metastasis), FAT1 (fatty acid metabolism) and IREB2 (Iron-responsive element)." (PMID 38206305, 2024).
tumor (continued). "Next, we verified the expression of A20/ACSL4 in the tumor by immunohistochemistry, the expression of the ferroptosis marker PTGS2, and the obvious effect of Apatinib + miR-214-3p inhibitors on tumor angiogenesis by CD34." (PMID 38370339, 2024). "IHC analysis of the tumor model showed LHPP knockdown increased AKT phosphorylation and decreased ACSL4 levels." (PMID 39261475, 2024). "Unsurprisingly, the levels of ferroptosis-related biomarkers ACSL4 and COX2 were most significantly elevated in SOR@TF-Fe3+ NVs-treated tumor cells, as determined by qPCR and Western blotting (for gel source data)." (PMID 37391845, 2023). "Further studies have reported that intercellular interactions lead to ferroptosis in tumor cells by mediating the NF2-YAP pathway and that YAP promotes the transcription of key ferroptosis genes such as ACSL4 and TFRC." (PMID 37266433, 2023). "Meanwhile, multiple oncoproteins and tumor suppressors promote this phenomenon and iron death proteins such as GPX4, ACSL4 and PTGS2 can be utilized in anti-tumor." (PMID 37542283, 2023). "We found that ACSL4 was down-regulated in RCC through the TCGA-KIRC project and our own collection of tumor tissues." (PMID 36923928, 2023). "Finally, knockdown of ACSL4 could reverse the tumor-promoting effect of ACSL4 in CHOL." (PMID 37193981, 2023). "T-cell-derived IFN-γ combines with arachidonic acid to activate ACSL4, and the activated enzyme increases the levels of PUFA in the cell membrane, thereby changing the lipid distribution pattern of tumor cell membranes." (PMID 37064872, 2023). "ACSL4, long chain acyl-CoA synthetase, has been shown to be able to stabilize c-Myc expression and promote tumour cell proliferation and tumour progression in HCC, and patients with high expression of ACSL4 have poorer RFS." (PMID 36737737, 2023). "Further investigation into the mechanism of the lipid-lowering effects of ECD revealed that it downregulated ACSL4, ACSL1, CPT1A, and FASN levels in colorectal tissues and downregulated tumor formation in the colorectum." (PMID 37078067, 2023). "We noted a dramatically high mean H score for ACSL4 and AKR1B10 in tumors compared to normal liver (mean tumor H score minus mean normal H score were 105.5 and 185.0 respectively)." (PMID 36829466, 2023). "Consistent with previous reports, the expression of ACSL4 and GPC3 was increased, and the expression of MT1G and SLC22A1 was decreased in the tumor tissues." (PMID 38188684, 2023). "Additionally, in both breast tumor cells and animal models, the use of PRGL493, a chemical inhibitor of ACSL4 impeding de novo steroid synthesis, could block cell proliferation and tumor growth, and promote the sensitivity of tumor cells to chemotherapeutic and hormonal treatment." (PMID 35910359, 2022). "The amount of ACSL4+ cells of the GFAP+ cells increased significantly by an average of 29.3% (p<0.001) between primary and relapsed tumor." (PMID 35530303, 2022). "An important factor that determines tumor cell survival is the close interaction between ACSL3, ACSL4, and ferroptosis." (PMID 36497375, 2022). "We further found that ferroptosis was involved in the process of tumor cell death, in which ferroptosis marker GPX4 was significantly decreased and ACSL4 was significantly increased." (PMID 35366904, 2022). "By detecting ACSL4 expression in HCC cells with miR-23a-3p mimics or Anti-miR-23a, and 23-KO HCC tumour tissues, it was found that miR-23a-3p negatively regulated the mRNA and protein expression of ACSL4 in HCC cells and tumour tissues." (PMID 34980204, 2022). "The heatmap showed that more than half of the genes were downregulated in tumor tissue, and consistent with the univariate Cox regression analysis, they represented a better prognosis, including PTGS2, ACO1, DPP4, CRYAB, PRKCA, ACSL4 and AKR1C3." (PMID 34475496, 2021).
tumor (continued). "Conversely, rosiglitazone, an inhibitor of ACSL4 which catalyzes PUFA incorporation into PLs, mitigated the in vivo elimination of tumor cells in RSL3-administrated mice." (PMID 33432112, 2021). "Further studies have found that PIR inhibits lipid peroxidation by regulating the expression of acyl-CoA synthetase long-chain family member 4 (ACSL4) and ultimately affecting the tumours growth." (PMID 34503532, 2021). "Mechanistically, ACSL4 can stabilize c-Myc expression at a post-transcription level in an ERK/FBW7-dependent manner, resulting in elevated tumor cell proliferation and enhanced tumor progression." (PMID 32350243, 2020). "The protein levels of O-GlcNAc, ACSL4 and GLUT1 were all elevated in tumour tissues compared with adjacent normal tissues." (PMID 32357142, 2020). "Suppressing ferroptosis by manipulating key ferroptosis regulators in tumor cells, such as GPX4 and acyl-CoA synthetase long chain family member 4 (ACSL4), reduces necrosis and dampens tumor aggressiveness." (PMID 33110073, 2020). "Coincidently, in the present study, we also revealed that ACSL4 promotes HCC via increasing cell proliferation and in vivo tumour growth and reducing cell apoptosis." (PMID 32357142, 2020). "Inhibiting ferroptosis by manipulating essential regulatory genes, such as GPX4 and ACSL4, curtailed GBM aggressiveness and prolonged the survival of tumor-bearing mice." (PMID 33110073, 2020). "We have demonstrated earlier that the combinatorial therapy with aspirin and sorafenib decreased the expression of ACSL4 and increased the expression of GADD45B to result in the inhibition of tumor growth." (PMID 28900541, 2017). "Induction of ACSL4 expression promotes the tumor progression in xenograft model, and the combination of ACSL4, LOX-5 and COX-2 inhibitor effectively reduces the tumor formation in vivo." (PMID 27171439, 2016). "In our interpretation of these data, the inhibition of ACSL4 might force the tumor to restore the estrogen signaling pathway for continuous growth and hormonal sensitivity, which is why the blockade of both the ACSL4 and estrogen pathways together might leave the tumor with extremely few options." (PMID 26536660, 2015). "Inmunohistochemical analysis of the tumor from animals inoculated with MCF-7 Tet-Off empty vector and from from animal inoculated with MCF-7 Tet-Off/ACSL4 and treated with doxycycline showed almost all cells expressing ERα and PR respectively." (PMID 22808264, 2012). "We examined the effect of a combination of inhibitors of ACSL4, LOX-5 and COX-2 on MDA-MB-231 tumor xenografts." (PMID 22808264, 2012). "The MDA-MB-231 is therefore the natural model to investigate if a combinatorial therapy targeting ACSL4, COX and LOX is effective in reducing tumor growth." (PMID 22808264, 2012). "The logical next step was to analyze the effect of ACSL4, COX-2 and LOX inhibitors on tumor growth in vivo." (PMID 22808264, 2012). "This implies that ACSL4, LOX-5 and COX-2 interact functionally and represent an integrated system that operates in a concerted manner to regulate tumor growth and consequently the proliferation and metastatic potential of cancer cells." (PMID 22808264, 2012). "In vivo anti-tumor studies performed on 4T1 tumor-bearing mice demonstrated that the synergistic effect of O2-enriched SDT and ACSL4 effectively increased the sensitivity to ferroptosis, significantly inducing cancer cell death and inhibiting tumor proliferation." (PMID 39744220, 2025). "Based on these studies, it is believed that increasing the enzymatic activity of ACSL4 will provide sufficient 'fuel' for LPO, which, in conjunction with the abundant ROS generated by SDT, could trigger effective ferroptosis tumor therapy." (PMID 39744220, 2025). "We found that ACSL4 could promote the malignant progression of NPC, and enhanced the tumor radiosensitivity through ferroptosis." (PMID 40050614, 2025).
tumor (continued). "ACSL4 also remodels the lipid profile in hepatocytes adjacent to tumors by increasing PUFA-containing lipids, which induces hepatocyte senescence and subsequently promotes tumor progression." (PMID 41288931, 2025). "Furthermore, ACSL4 modulation via deubiquitination has been demonstrated to promote HCC by influencing FA biosynthesis, lipid peroxidation, and the tumor immune microenvironment." (PMID 41288931, 2025). "In vivo, PRGL493 treatment suppressed tumor growth in ZR-75-BQ xenografts, but did not affect the body weight, highlighting the translational potential of targeting ACSL4 in BQ-high tumors and supporting the safety of PRGL493 at the administrated dose." (PMID 40507798, 2025). "However, DDR1 knockdown significantly reduced GSH levels and GPX4, SLC7A11 and ZEB1 expression and increased MDA and Fe2+ levels, as well as ACSL4, E‐cadherin, p‐YAP and p‐NF2 expression levels in tumour tissues." (PMID 40105492, 2025). "Therefore, changes in the expression and activity of key enzymes regulating PUFA metabolism, such as ACSL4 and LPCAT3, directly affect the "flammability" of tumor cells." (PMID 41201667, 2025). "Re-expression of ACSL4 also sensitized the response to cisplatin or radiation only in bulk tumor cells but not in TRCs." (PMID 38720107, 2024). "Using tumor samples derived from the tumor xenograft mouse model, we demonstrated that the expression of FSP1, ki67, SOD2, and ACSL4 proteins was significantly suppressed in the FSP1 inhibition and combined treatment groups compared with that in the control group." (PMID 38206305, 2024). "Tumor cells might dynamically regulate the expression of ACSL3 and ACSL4 to fulfill specific metabolic demands or adapt to environmental stressors." (PMID 39744125, 2024). "Intriguingly, combinatory treatments of irradiation and ACSL4 KO or pairing liproxstatin-1 effectively reduced occurrence of ferroptosis without affecting other impact of irradiation on tumor inhibition." (PMID 38323315, 2024). "Given that the protein levels of ACSL4 and LPCAT3 were similar between TRCs and bulk tumor cells, we tested whether there were differences in the enzymatic activity." (PMID 38720107, 2024). "In addition, fatty acids play a coordinating role in triggering ferroptosis in tumor cells and modulating the immune response involving CD8+ T cells through acyl-CoA synthetase long-chain family member 4 (ACSL4)." (PMID 38672455, 2024). "Here we not only establish that miR-211 is downregulated in non-WNT MB and has a tumor suppressive role but also identify ACSL4 as a direct target." (PMID 38115140, 2023). "Interestingly, ACSL4 R339me2a expression was significantly negatively correlated with lipid ROS and MDA levels in CRC tumor tissues of patients." (PMID 37946697, 2023). "Recently, it was reported that ACSL4 promotes cancer progression and, therefore, ACSL4-dependent ferroptosis does not necessarily represent tumor suppression." (PMID 37237981, 2023). "But ACSL4-dependent ferroptosis does not account for the tumor promotion of ACSL4 in CHOL, just like the previous study in HCC." (PMID 37193981, 2023). "Similar results can be observed by IHC staining of ACSL4, GPX4, and SLC7A11 in subcutaneous tumor." (PMID 37993428, 2023). "Based on GSEA and CIBERSORT analysis, tumor cells with low GPX4 tend to be infiltrated by higher proportion of CD4+ T cell, expression of NOX1 was negatively correlated with M1 macrophage infiltration and ACSL4 was positively close to CD8+ T cell infiltration." (PMID 35855531, 2023). "Second post-CIR time point identified cullin 7 (CUL7) and last time point acyl-coa synthetase long chain family member 4 (ACSL4) with NF2, OBSL1 and YWHAE as highly connected components, all being described or hypothesized to play roles in tumor development." (PMID 35158950, 2022).
tumor (continued). "The protein level of ferroptosis-related genes was verified by the HPA database and IHC test, leading to the discovery that the expressions of ALOX5, PEBP1, ACSL4, and ZEB1 proteins up-regulated in tumor tissues, and existed differences between tumor tissues and normal tissues." (PMID 36313708, 2022). "We show that ACSL4-dependent ferroptosis in the liver does not function as an endogenous tumor suppressor but rather promotes HCC progression following chronic liver damage." (PMID 35963845, 2022). "Long-chain acyl-CoA synthetase-4 (ACSL4) is involved in fatty acid metabolism, and aberrant ACSL4 expression could be either tumorigenic or tumor-suppressive in different tumor types." (PMID 34053456, 2021). "In addition, ACSL4 was found to act as a tumor suppressor and a favorable prognostic factor in patients with LUAD and promoted ferroptosis but inhibited tumor cell survival, invasion, and migration." (PMID 34926310, 2021). "Tissue microarray analysis revealed that phosphor 4EBP1 staining correlated with GPX4 level, but not ACSL4 level, in tumor samples from cancer patients." (PMID 33707434, 2021). "In clear contrast, the genes involved in FA desaturation (stearoyl-CoA desaturase, SCD5) and PUFA trafficking (fatty acid-binding protein 7, FABP7; acyl-CoA synthetase 4, ACSL4; phospholipase A2G2D, PLA2G2D) were upregulated in tumours with PI(18:0/20:3) accumulation." (PMID 31819188, 2020). "Therefore, it would be interesting to elucidate how the coordination of FABP7, ACSL4 and PLA2G2D in tumour microenvironment modulates the remodelling of membrane lipids as well as tumour immunity." (PMID 31819188, 2020). "Neither ACSL3 nor ACSL4 were detected on the surface of lipid droplets in either normal liver tissue or in non-HCC tumour cells in any of the samples examined." (PMID 32286604, 2020). "However, it exists that some snoRNAs are potent enough to act in a single manner like SNORD113-1, which operates as a tumor suppressor role in HCC, in a cohort of patients where ACSL4 is overexpressed." (PMID 33050166, 2020). "Transferrin receptor-1 and ACSL4 increased slightly in the neratinib-treated group but were not significantly different from control tumours." (PMID 31409375, 2019). "In ER-negative breast tumor samples, high ACSL4 expression predicted a shorter time to distant metastases and was highest in triple negative breast cancer cell lines and tumor samples that lacked AR receptors." (PMID 26636648, 2015). "Although the role of acyl-CoA synthetase 4 (ACSL4) in mediating an aggressive phenotype is well accepted, there is little evidence as to the early steps through which ACSL4 increases tumor growth and progression." (PMID 26536660, 2015). "Based on our results, we hypothesized that ACSL4, LOX-5 and COX-2 may constitute potential therapeutic targets for the control of tumor growth." (PMID 22808264, 2012). "We hypothesized that ACSL4, LOX-5 and COX-2 may constitute potential therapeutic targets for the control of tumor growth." (PMID 22808264, 2012). "Studies suggest that targeting lipid metabolism pathways, such as inhibition of fatty acid synthase (FASN) or acyl-CoA synthetase long-chain family member 4 (ACSL4), could promote ICD by increasing lipid peroxidation and enhancing the immunogenicity of tumor cells." (PMID 40299564, 2025).